SOX2 (SRY-box transcription factor 2)
Diseases named in the same sentence as SOX2 in open-access papers (continued):
Sharing a sentence is not in itself a finding about the gene and the disease.
glioma (continued). "To confirm that the relative amount of SOX2 mRNA is translated into appropriate protein levels, we performed indirect immunofluorescence analyses of U343 and U373 glioma cells as well as of 93.04A12.1-melanoma cells using a monoclonal anti-SOX2-antibody." (PMID 17375044, 2007). "Functional studies showed that FLG knockdown increased GSC-associated markers (Oct4, 2.1-fold; SOX2, 1.8-fold) and enhanced TMZ resistance, whereas cp8 treatment reduced MGMT protein expression by 68% and significantly decreased glioma sphere size by 54% (p < 0.01)." (PMID 41943081, 2026). "In addition, our previous studies confirmed Sox2 expression level as a marker of the effectiveness of rat glioma 101.8 therapy with the cytostatic doxorubicin." (PMID 41009560, 2025). "Additionally, in hepatocellular carcinomas, gliomas, and colorectal cancers, SOX2 has been shown to induce mesenchymal–epithelial transition and promote invasion." (PMID 41012776, 2025). "ELF4 knockout mice have impaired neurosphere formation and slow glioma growth, and ELF4 may promote the growth of gliomas by upregulating Sox2." (PMID 41300273, 2025). "We found a high expression level of Sox2 (sex-determining region Y-box 2) in rat glioma 101.8." (PMID 41009560, 2025). "Moreover, the SOX2/OCT4 signaling pathway can suppress the apoptosis of glioma cells by inhibiting the activity of pro-apoptotic factors (i.e., BAD and CASPASE), thereby further enhancing the malignant progression of glioma cells." (PMID 39781344, 2025). "To clarify the novelty of this study relative to our 2023 preprint (“Long non-coding RNA ZFHX4-AS1 Upregulates the Neural Differentiation-related Gene ZFHX4 and thereby Promotes SOX2 Expression to Accelerate Glioma Progression”), we provide a side-by-side comparison of the core findings." (PMID 41458623, 2025). "Changes in NOTCH1 and SOX2 were present in all glioma types." (PMID 40679044, 2025). "We also detected ZFHX4 expression in glioma cells that overexpressed and knocked down SOX2." (PMID 41458623, 2025). "Furthermore, the immunohistochemistry analysis of 17 glioma specimens revealed a notably higher incidence of positive expression for SOX2 and PIK3R3 in GBM tissues compared to I‐III glioma tissues." (PMID 39968701, 2025). "This link suggests that targeting the Notch pathway could be a possible therapeutic option in SOX2-related diseases like glioma." (PMID 40227667, 2025). "The ZFHX4-AS1/ZFHX4/SOX2 axis represents a promising set of targets for glioma intervention." (PMID 41458623, 2025). "We also verified the expression of SOX2 in glioma tissues and cells." (PMID 41458623, 2025). "SOX2 is a master regulator crucial for maintaining stem cell identity, including in glioma." (PMID 40422249, 2025). "A high level of SOX2 expression was also observed in glioma cells." (PMID 41458623, 2025). "In addition, lncRNA PVT1 sponges miR-365 to up-regulate ELF4, which in turn serves as an upstream regulator of SOX2, thereby facilitating the stemness features and temozolomide resistance of glioma." (PMID 40083328, 2025). "Furthermore, overexpression of SOX2 followed by knockdown of ZFHX4 reversed the malignant biological behavior of glioma cells, such as proliferation, migration and invasion." (PMID 41458623, 2025). "Hence, rat glioma 101.8 is potentially a quite reliable preclinical model to evaluate the anti-tumor efficacy of SOX2-, OLIG1/2-, and PDGFRA-targeting therapy approaches." (PMID 41009560, 2025). "Moreover, high levels of SOX2 expression in glioma cells are often correlated with increased tumor grade and aggressiveness." (PMID 38398118, 2024). "Moreover, IHC staining of human glioma samples confirmed a positive correlation between EphA2 and both SOX2 and CD133." (PMID 39346536, 2024). "In addition, METTL3 silencing in GSC cells METTL3 resulted in reduced expression of glioma reprogramming factors, including SOX2 (SRY-box 2)." (PMID 38398118, 2024).
glioma (continued). "Interestingly, rapamycin decreased SOX2 mRNA expression in glioma U251 and U373 cell lines and inhibited U251 glioma tumor growth in mice." (PMID 38612911, 2024). "A previous study on glioblastoma showed that knockdown of MerTK disrupted the rounded morphology of glioma cells with a decrease in tumor stem cell markers, such as Sox2 and Nestin, indicating that MerTK could maintain cells in an undifferentiated state." (PMID 38545840, 2024). "Moreover, SOX2 can lead to glioma formation, and SOX2-KO mice demonstrated inhibition of glioblastoma development and tumorigenicity, suggesting that this transcription factor is crucial for the preservation of self-renewal balance." (PMID 39547513, 2024). "Additionally, our results revealed that high OCT4 expression in glioma stem cells is accompanied by increased expression of another essential glioma stem cell gene, SOX2." (PMID 39588508, 2024). "SNHG6 regulated the progression of glioma through upregulation of Notch1, Sox2, and EMT." (PMID 38194709, 2024). "Based on the fact that GSCs are important for chemotherapy resistance in glioma 7, 41, we decided to verify whether blocking the GSCAR/DHX9-IGF2BP2/SOX2 feedback loop could increase the glioma cell response to TMZ." (PMID 37063420, 2023). "We identified the SOX2-PML axis as a key regulator of HCMV infection in glioma cells and demonstrated in a patient-derived xenograft mouse model that the SOX2-PML axis not only controls HCMV infection but also contributes to the oncomodulatory role of the virus." (PMID 37058447, 2023). "First, SOX2 expression positively correlated with (P)RR expression in human glioma tissues." (PMID 36646875, 2023). "In addition, there was a high abundance of cells across the entire brain displaying an increased expression of glioma stem cell marker SOX2 (middle row)." (PMID 37370741, 2023). "Given that SOX2 is a transcription factor, we wondered whether SOX2 acts indirectly via its downstream target genes in glioma cells." (PMID 37058447, 2023). "The aberrantly high expression of SOX2 in GSCs prompted us to investigate whether SOX2 shapes HCMV infection in gliomas." (PMID 37058447, 2023). "Large actin-rich glioma cells were positive for Axl, integrin αvβ5, Sox2, and Oct4." (PMID 37833934, 2023). "In our GBM mouse models, elevated SOX2 expression enhances HCMV’s oncomodulatory effects, suggesting that combinatorial expression profiling of IE1 and SOX2 may have prognostic value in patients with gliomas." (PMID 37058447, 2023). "Together, these data provide clinical findings in support of our hypothesis that the SOX2-PML axis regulates HCMV gene expression in gliomas." (PMID 37058447, 2023). "That is, Sox2 regulated glioma cell dedifferentiation under hypoxic conditions." (PMID 34976166, 2022). "In addition, Sox2, another factor, was studied in this article and found to be an ideal target for glioma treatment because it was highly expressed in glioma but expressed at low levels in normal tissues." (PMID 34976166, 2022). "SOX‐2 is also a common marker in cancer stem cells, which may be involved in the chemoresistance of glioma cells." (PMID 36184801, 2022). "In addition, HIF-2α promoted glioma cells migration under hypoxia by activating an Oct-4/Sox-2-MenaINV axis." (PMID 36620546, 2022). "miR-145 could interact with circITCH to regulate its target gene RASA, promoting the progression of ovarian cancer.miR‐145 regulates the SOX2-Wnt/β-catenin axis to enhance chemosensitivity to demethoxycurcumin in gliomas." (PMID 36059813, 2022). "In our study, we defined glioma stem cells by CD133 (PROM1) or SOX2 protein expression using semiquantative immunohistochemistry, recognizing that additional computational approaches may be more widely available in the near future." (PMID 36333778, 2022). "Thus, we profiled Sox2 + glioma cells to capture rare GSC populations, that can be vanished in big studies observing all cells within a tumor." (PMID 36348001, 2022).
glioma (continued). "Inhibiting glioma cell stemness through the Nanog/Sox2/CD133 pathway can halt gliomagenesis." (PMID 35269752, 2022). "We found that the basic level of SOX2 mRNA significantly differs in glioma cells." (PMID 36231068, 2022). "Additionally, the proportion of Sox2 + cells in wt-cultures was around 50%, and almost all cells displayed intensive intra nucleus staining, while IDH1mt glioma cells revealed sparse Sox2 staining localized in both cell nucleus and cytoplasm." (PMID 36348001, 2022). "These cells usually express some specific stem markers, like CD-133, OLIG2, and SOX2, in gliomas." (PMID 36338770, 2022). "In glioma the rate of Sox2 expression correlates positively with the grade of malignancy." (PMID 35183162, 2022). "In order to elucidate whether the expression of SOX2 and SOX3 affected the proliferation and invasion of glioma cells, we downregulated the expression of SOX2 and SOX3 to observe the changes of migration and invasion ability of U251 cells." (PMID 34953010, 2022). "Similarly, Western blotting revealed very high expression of SOX2 in freshly derived glioma stem cell (GSC) cultures from human patients and in U251MG and U373MG cell lines, while A172, T98G and U87MG expressed low levels." (PMID 33805518, 2021). "More importantly, we identified that collagen/FN stimulated glioma progression through integrin αvβ3-induced PI3K/AKT/SOX2 and CDC42/F-actin/YAP-1/Nupr1/Nestin double signal activation simultaneously, expounding the underlying mechanism of the extracellular matrix-induced tumor signaling network." (PMID 33408794, 2021). "The inhibitory effects of NC on the expression of Oct4, Sox2, and Bim1 along with other stem cell markers in glioma may reduce the growth of glioma stem‐like cells and improve the survival rate of glioma patients." (PMID 33788424, 2021). "In the adult nervous system, SOX2 is expressed in NSCs and undifferentiated precursor cells, and in cancer SOX2 serves as a marker of proliferating or undifferentiated cells in human malignant gliomas, including pediatric gliomas, and ependymomas." (PMID 34012965, 2021). "EPHA2 also contributes to human glioma stem cell formation and stemness marker SOX2 expression." (PMID 33436772, 2021). "SRR2 deletion by CRISPR/Cas9 technology leads to a reduction in SOX2 expression in glioma cells." (PMID 33805518, 2021). "Together, those results indicated that suppressing SOX2 and Nestin signaling by the integrin αvβ3 inhibitor efficiently improved the anticancer effects of the conventional chemotherapeutic agent, providing an innovative approach in glioma therapy." (PMID 33408794, 2021). "In addition, an autocrine TGF-β loop maintains the self-renewal capacity of glioma-initiating cells, by directly targeting the SOX2 transcription factor." (PMID 33576874, 2021). "Furthermore, we observe that ablation of HDAC1 function in GSCs suppressed expression of key glioma stemness markers like SRY-box transcription factor 2 (SOX2), Nestin, and oligodendrocyte transcription factor 2 (OLIG2)." (PMID 34494550, 2021). "Expression of Sox2 and Oct4 is positively correlated with the pathological grade of glioma." (PMID 33788424, 2021). "Our in vitro results demonstrated that 3D collagen/FN culture could induce the PI3K/AKT and CDC42/YAP/NUPR1 signal activation in glioma cells, resulting in growth factors SOX2/Nestin up-regulation." (PMID 33408794, 2021). "GISTIC 2.0 analysis revealed that in gliomas with high-risk scores, the amplification mainly occurred in chromosomal regions 1q32.1, 3q26.33, 4q12, 7p11.2, and 12q14.1, where several key oncogenes (PDGFRA, EGFR, MDM2, SOX2, and CDK4) were located." (PMID 35116021, 2021). "To further explore this relationship and to evaluate whether there is bidirectional regulation, i.e., Notch1 and Sox2 can themselves regulate SNHG6 in glioma cells, we silenced Notch1 and Sox2 using specific siRNAs against them and measured SHHG6 levels." (PMID 34485294, 2021).
glioma (continued). "We prove that SRR2 deletion leads to a reduction in the expression of SOX2 in glioma cells." (PMID 33805518, 2021). "The over-expression of ID4 in glioma stem cells directly inhibited the expression of microRNA-9 by inhibiting the expression of SOX2, which in turn regulated ATP-binding cassette (ABC) transporters, finally leading to less sensitivity to nitrosourea drugs in cancer cells." (PMID 32328189, 2020). "NEAT1 facilitated cell migration and invasion in glioma by regulating SOX2 via sponging miR-132." (PMID 32883232, 2020). "Additionally, MALAT1 promoted glioma growth in a xenograft mouse model through regulation of miR-129 and SOX2." (PMID 32650527, 2020). "To interrogate the functional significance of SATB2 expression in GBM malignant growth, we initially examined SATB2 expression pattern in several human GBM specimens and found that SATB2 is preferentially expressed in nuclei of glioma cells expressing the GSC markers SOX2 and OLIG2." (PMID 33124191, 2020). "Besides the high proliferation rate, one feature that characterizes glioma aggressiveness is the expression of different stem cell markers such as SOX2 and Oct4." (PMID 33081024, 2020). "The integration phenomenon and its subsequent effects on the cell fate are worth the investigation since some studies have proved that in GBM, SOX2 gene amplification contributes toward upregulation of promotor hypo-methylation, invasive migration of glioma and self-regulation of cancer stem cells." (PMID 32092088, 2020). "Indeed, Nanog functionally cooperates with SOX2 not only in ESCs maintenance, but also in germ cell-derived tumors, in various carcinomas and gliomas, and in reprogramming settings." (PMID 32664542, 2020). "For cases with SOX2 high expression in the primary glioma, those had SOX2 low expression after recurrence seemed to have worse prognosis as compared to patients with stable SOX2 high expression (PFS: 10.4 vs. 14.9 months, p = 0.036; OS: 27.0 vs 49.5 months, p = 0.005)." (PMID 31718604, 2019). "The expression of SOX2 decreased in recurrent gliomas compared with the primary gliomas." (PMID 31718604, 2019). "Moreover, miR-26a alleviated the inhibitory effect of AP-2α and the miR-26a inhibitor on glioma cells by upregulating the expression of Nanog/Sox2 and the IL6/Jak2/STAT3 signaling pathway." (PMID 31534499, 2019). "The change of SOX2 expression after adjuvant therapy in high grade glioma (HGG) remains unknown so far." (PMID 31718604, 2019). "Notably, silencing of SIX1, using two independent shRNAs, led to a marked reduction in SOX2 transcript and protein in both glioma cell lines, in line with the results in mouse transformed fibroblasts." (PMID 30723235, 2019). "Moreover, functional analyses with human glioma cell lines also show that SIX1 controls SOX2 expression, senescence and self-renewal in this model." (PMID 30723235, 2019). "In patients with SOX2 high expression in primary glioma, 13 cases (54.2%) changed to SOX2 low expression after recurrence, the prognosis of these patients seemed worse than patients with stable SOX2 expression (PFS: 10.4 vs. 14.9 months, p = 0.036; OS: 18.5 vs 32.8 months, p = 0.249)." (PMID 31718604, 2019). "Therefore, SOX2 gene is the key gene for the maintenance of the characteristics of glioma stem cells." (PMID 31718604, 2019). "Moreover, the reduced expression patterns of stemness-associated genes (MYC and SOX2) and the reactivation of neuronal differentiation-associated genes (BDNF, NGF, and NTF3) were clearly observed in the asTUG1/uPIC-treated glioma tissues." (PMID 31019193, 2019). "Those patients with SOX2 expression decreased in recurrent glioma often had worse prognosis." (PMID 31718604, 2019). "Indeed, previous studies have suggested that SOX2 protein is significantly more widely expressed in glioma tissue than in normal brain, with expression in the adult brain being typically restricted to ventricular stem cell niches." (PMID 30041684, 2018).
glioma (continued). "After knocking down SOX2, the viability and aggressiveness of glioma cells significantly decreased." (PMID 30053878, 2018). "NEAT1 and SOX2 knockdown successfully reduced the invasiveness of glioma cells." (PMID 30053878, 2018). "MiR-132 was down-regulated while SOX2 was up-regulated in glioma cells." (PMID 30053878, 2018). "Therefore, we investigated the interaction between lncRNA NEAT1, miR-132 and SOX2 in glioma and identified their roles in glioma." (PMID 30053878, 2018). "Of note, we recently and firstly showed a high and significant correlation between NOS2 and SOX-2 expression in glioma cells.Collectively, all of these studies, among others, suggest that NO signaling plays an important role in GSC maintenance and resistance to anticancer therapies." (PMID 30227679, 2018). "NEAT1 promoted glioma development by promoting SOX2 expression through suppressing miR-132." (PMID 30053878, 2018). "The interactions between NEAT1, miR-132 and SOX2 in glioma were also novel findings." (PMID 30053878, 2018). "Silencing SOX2 in glioma cells had similar inhibitory effects as NEAT1 knockdown." (PMID 30053878, 2018). "The tumor promotive effect of SOX2 in glioma was reported in many previous studies." (PMID 30053878, 2018). "As a target gene of miR-132, SOX2 was over-expressed in glioma." (PMID 30053878, 2018). "NEAT1 knockdown could down-regulate SOX2 by up-regulating miR-132, thus suppressing glioma cell growth and invasiveness." (PMID 30053878, 2018). "To examine whether Smad6 contributes to STAT3 activation, we first analyzed proteins downstream of STAT3 associated with glioma stemness, including c-jun, CCND1, and Sox2." (PMID 29950561, 2018). "Consistent with this hypothesis, it has been previously demonstrated that SOX2 mRNA expression was greater in lower grade gliomas." (PMID 29963265, 2018). "Moreover, a high and significant correlation was observed among the expression of NOS2 and SOX-2 (Sex determining region Y-box 2), which is a stemness marker that is aberrantly upregulated in both human glioma cell lines and primary cultures." (PMID 30227679, 2018). "While the pervasiveness of SOX2 is inconsistent with the idea that this protein marks a rare subpopulation of stem-like cells in HGG, the role of SOX2 in pluripotency implies that the majority of transformed glioma cells are in an immature and potentially plastic state." (PMID 30041684, 2018). "In glioma, SHP2 regulates glioma stem cells proliferation and tumorigenicity via targeting SOX2." (PMID 29983715, 2018). "Meanwhile, SOX2 could be up-regulated by miR-132 inhibitor and down-regulated by miR-132 mimics in glioma cells, demonstrating the negative regulatory effect of miR-132 on SOX2 expression." (PMID 30053878, 2018). "NEAT1 knockdown could inhibit the growth and invasiveness of glioma cells through indirectly down-regulating SOX2 by targeting miR-132." (PMID 30053878, 2018). "The detection of these proteins together to stem cell markers (CD133, CD44, and Sox2) may help to discriminate glioma cells to glioma stem-like cells." (PMID 29486795, 2018). "On the contrary, MKP1 levels were reduced in glioma cells with elevated SOX2 or SOX9 activity." (PMID 29284798, 2017). "In addition, even owing to our previous experience on the role of SOX-2 in human glioma primary cultures, we have also analyzed the potential correlation between NOS2 and SOX-2 in both glioma primary cultures and derived neurospheres." (PMID 28424427, 2017). "We noticed that some gB positive cells (green color) exhibit CD11B-negative/CD45-negative phenotype (green color), and the majority of gB positive cells represent a OLIG2-positive subclass of glioma cells (yellow signal of colocalization) or exhibit strong expression for SOX2." (PMID 27517625, 2017). "Sox2 activation was also found in glioma cells in 3D culture, and MGMT activation may be induced by Sox2." (PMID 27486877, 2016).